ZNF347 (zinc finger protein 347)
Description:
May be involved in transcriptional regulation.
Synonyms: ZNF1111
Tractability: PROTAC: UniProt records ubiquitination sites on it; ubiquitination databases record sites on it.
Gene: Protein-coding gene on chromosome 19 (53,124,072 to 53,159,075, reverse strand). Ensembl gene ENSG00000197937.
Subcellular location: Nucleus
Subcellular location (Human Protein Atlas): Microtubules
Pathways (Reactome):
Gene expression (Transcription): Generic Transcription Pathway
Gene Ontology:
Molecular function: DNA-binding transcription factor activity, RNA polymerase II-specific; RNA polymerase II cis-regulatory region sequence-specific DNA binding; sequence-specific double-stranded DNA binding
Biological process: regulation of transcription by RNA polymerase II; regulation of DNA-templated transcription
Cellular component: nucleus
Genetic constraint (gnomAD): Loss-of-function variants: 20 observed, 14.51 expected, observed/expected ratio (o/e) 1.38, 90% interval 0.96 to 1.87. The upper end of that interval is the gene's LOEUF score, 1.87, which puts it in group 6 of 6, group 1 being the genes least tolerant of losing a copy. Missense variants: 1,004 observed, 1,025.2 expected, observed/expected ratio (o/e) 0.98, 90% interval 0.93 to 1.03. Synonymous variants: 328 observed, 348.45 expected, observed/expected ratio (o/e) 0.94, 90% interval 0.86 to 1.03.
Homologues: Orthologues: chimpanzee ZNF347 (99% identical), zebrafish znf646 (21% identical), zebrafish si:dkey-89b17.4 (19% identical), Drosophila melanogaster zf30C (19% identical), Drosophila melanogaster CG18011 (18% identical), zebrafish znf576.1 (18% identical), Drosophila melanogaster CG6791 (16% identical), Drosophila melanogaster CG30020 (15% identical), Drosophila melanogaster hang (14% identical), Caenorhabditis elegans ztf-15 (14% identical), Drosophila melanogaster CG1602 (13% identical), Drosophila melanogaster mld (13% identical), and 20 more. Paralogues in human: ZNF160 (64% identical), ZNF665 (51% identical), ZNF91 (45% identical), ZNF845 (45% identical), ZNF208 (42% identical), ZNF107 (41% identical), ZNF184 (41% identical), ZNF99 (41% identical), ZNF729 (40% identical), ZNF420 (40% identical), ZNF84 (38% identical), ZNF569 (36% identical), and 24 more.
Diseases named in the same sentence as ZNF347 in open-access papers:
ZNF347 is named in the same sentence as 5 diseases in open-access papers, as found by Europe PMC text mining. Sharing a sentence is not in itself a finding about the gene and the disease. The quoted sentences say what the papers report.
breast carcinoma (1 paper, 2025). "The ZNF347 expression in 6D cells could contribute to the acquisition of invasive features, as this protein has been classified as a predictor of lymph node metastasis from primary breast cancer tumors." (PMID 40429863, 2025).
cancer (2 papers, 2021 to 2022). A tumor composed of atypical neoplastic, often pleomorphic cells that invade other tissues. "Finally, OV_sBRCA2 was characterized by the up-regulation of zinc finger proteins (ZNF613, ZNF329, ZNF530, ZNF347), a gene family known to be involved in pathways of carcinogenesis, cancer progression, and metastasis formation." (PMID 33525353, 2021).
ZNF347 also shares sentences with these, for which no sentence is quoted: head and neck cancer (1 paper); oral cancer (1); tumor (1).